EGFR (epidermal growth factor receptor)
Diseases named in the same sentence as EGFR in open-access papers (continued):
Sharing a sentence is not in itself a finding about the gene and the disease.
tumor (continued). "Homozygous deletion was seen only at 9p21.3 including CDKN2A and limited to EGFR-mutated tumours among ALK fusion-negative neoplasms as reported in the literature and also seen in ALK-fusion positive ones." (PMID 23289484, 2013). "However, as therapy continues, more and more KRAS wild-type tumor are wiped out, the abundance of KRAS mutation becomes higher and patients tend to have a progression disease and become resistant to EGFR antibody therapy." (PMID 23874486, 2013). "Activation of EGFR signaling is also known to inhibit IP-10-mediated tumor cell migration." (PMID 23669876, 2013). "Since Mig6 played a consistent role across multiple tumor types, the Mig6/EGFR ratio may be further clinically tested as a novel biomarker for predicting TKI response (and perhaps antibodies to EGFR as well) in diverse epithelial cancers." (PMID 23935914, 2013). "Therefore in subsequent in vivo studies we used IgA2 EGFR to assess the anti-tumour activity of IgA antibodies." (PMID 23918228, 2013). "However, a limitation of this study is that there is a possibility of alterations in EGFR expression level during tumor progression." (PMID 23824671, 2013). "We observed that EGFR could locate on tumor cell membrane, in cytoplasm or both on membrane and in cytoplasm by immunohistochemical analysis." (PMID 23536868, 2013). "Importantly, the anti-tumour activity of both IgA1 and IgA2 EGFR ex vivo was fully dependent on the presence of FcαRI Tg." (PMID 23918228, 2013). "Interestingly, the EGFR antagonist cetuximab has proven effective even against EGFR-negative tumours." (PMID 24204699, 2013). "Importantly, despite the shorter half-life and incomplete opsonization, IgA2 EGFR efficiently mediated anti-tumour effects." (PMID 23918228, 2013). "Our data suggests that overexpression of EGFR protein might be due to the impairment of the SH3GL2 associated endocytosis mechanism, whereas down regulation of CDC25A in this tumor might lead to the EGFR protein in its active state." (PMID 23675485, 2013). "Thus, although our data are based on a relatively small number of patients, they clearly support the in vitro findings that EGFR/HER1 is suppressed by estrogen in tumours, leading to an inverse relationship between ER and EGFR/HER1." (PMID 23991224, 2013). "Also, tumor IHC revealed a marked downregulation of EGFR protein expression in the LPEI/siRNA-EGFR-treated group, and, as shown by western blot analysis, inhibitory efficiency was 55%." (PMID 27234384, 2013). "Hence, for these 7 genes (TS, FPGS, GGH, DHFR, ERCC-1, TOPO-1, and EGFR), evaluation of their expression by biopsy would reflect the mRNA expression in the whole tumor and would therefore permit their use in the clinic." (PMID 23577026, 2013). "Since galectins have been reported as being involved in tumor development, investigation of their interaction with phosphorylated EGFR (pEGFR)-Y845 and -Y1173 may also be important." (PMID 23449029, 2013). "However, treatment with EGFR-specific siRNA vectored by LPEI induced significant tumor growth inhibition." (PMID 27234384, 2013). "Tumor responsiveness to erlotinib could be better predicted in some tissue types by measuring expression levels of both EGFR and Mig6 than by measuring expression levels of either protein alone." (PMID 23935914, 2013). "EGFR expression and activation levels were decreased in tumor cells of mice treated with berberine." (PMID 23457600, 2013). "If KRAS harbors an activating mutation, agents acting on EGFR will not have any effect on tumor growth." (PMID 23555683, 2013). "The clinicopathological factors of age, gender, pathological tumor size, nodal status, lymphatic permeation and blood vessel invasion and the EGFR and KRAS mutation spectra were compared between never and heavy smokers." (PMID 24179496, 2013).
tumor (continued). "Thus, a major challenge in targeting these invasive, EGFR-activated tumor subpopulations will be to effectively deliver bioactive molecules across the BBB and at the same time inhibit potential angiogenic escape mechanisms." (PMID 23429996, 2013). "Immunoliposomes directed against multiple tumor antigens, for example, EGFR and VCAM-1 could, increase the therapeutic efficacy and, hereby, immunoliposomal therapy could become clinically significant as a novel treatment for cancer." (PMID 24175095, 2013). "In contrast, EGFR/HER1 was downregulated in tumour compared to normal tissue (0.13-fold, P<0.001)." (PMID 23991224, 2013). "It was reported previously that inhibition of EGFR signaling could induce apoptosis and inhibit growth of tumor cells." (PMID 24314030, 2013). "Several studies have demonstrated that IgA EGFR mediate potent anti-tumour effects in vitro." (PMID 23918228, 2013). "We observed lower tumour compared to normal tissue levels of EGFR/HER1." (PMID 23991224, 2013). "In a total of 345 patients the tumor samples were adequate for both EGFR and KRAS analysis." (PMID 23922984, 2013). "In addition, the fusion protein displayed EGFR-specific binding and the ability to kill EGFR-expressing tumor cells specifically." (PMID 23573299, 2013). "It has been proposed that EGFR signaling might play a role in the G2/M phase of the cell cycle in human tumor cell overexpressing EGFR." (PMID 23394599, 2013). "With regard to the carryover of genetic mutations from patient NSCLC tissues to mouse xenograft tissues, data from our study showed that genotypes are consistent between the original patient tumor and the corresponding xenograft tissue in all ten models for EGFR and KRAS status." (PMID 23842453, 2013). "The antiproliferative effects of erlotinib, arising from cell-cycle arrest, might render tumor cells less sensitive to cytotoxic agents, as suggested by recent preclinical studies of combinations of EGFR TKIs with chemotherapy." (PMID 24236082, 2013). "The enrichment of EGFR expression in ZEB1 positive tumours suggests that tumour treatment may be more efficacious via EGFR inhibition in combination with TMZ treatment." (PMID 23818228, 2013). "The paracrine signals that mediate the oestrogenic effects on CSC suggest a role for EGFR and Notch signalling in endocrine resistance and may offer suitable targets for treatment of these tumours." (PMID 23497505, 2013). "Thus, across the cell lines tested, the ratio of Mig6 to EGFR, appeared to be a more reliable predictor of tumor cell response to erlotinib than the absolute expression of either protein alone." (PMID 23935914, 2013). "Correspondingly, direct injection of a liposome-encapsulated miR-7 plasmid into established EGFR-TKI sensitive and resistant tumors bearing the T790M EGFR mutant resulted in significant tumor regression in conjunction with repression of EGFR, RAF-1 and IRS-1 expression." (PMID 24349829, 2013). "To study whether human IgA EGFR mediate anti-tumour activity by mouse effector cells ex vivo we used whole blood from G-CSF-stimulated FcαRI Tg and WT control mice as effector cells." (PMID 23918228, 2013). "In this context it is important to identify factors that contribute to EGFR-induced tumor cell growth because their targeting may help sensitizing cells to the activity of TKIs." (PMID 23896512, 2013). "Hence, we sought to describe the EGFR activation in our 10 tumor lines, studying the expression of phosphorylated EGFR (phospho-EGFR) and downstream signaling proteins (phospho-AKT and phospho-MEK1)." (PMID 23874590, 2013). "Given c-Met’s ability to promote tumor cell motility, invasion and resistance to EGFR-TKIs, c-Met inhibition has been hypothesized to limit tumor spreading and resistance to cytotoxic agents and targeted therapies." (PMID 24349829, 2013). "MiRNAs have been previously shown to interact with EGFR as both tumor suppressors and oncogenes." (PMID 23963114, 2013).
tumor (continued). "Instead, Talavera built a computer model of the nimotuzumab-EGFR complex, where nimotuzumab blocks ligand binding, but allows the receptor to adopt its active conformation, warranting the basal level of signaling needed for the survival of non-tumor cells." (PMID 23782513, 2013). "Different biological substrata might support EGFR addiction in different stages of the disease and in different tumor localizations, and in consequence, different response predictor and treatment selection biomarkers would be needed." (PMID 23637683, 2013). "Increased levels of GLI1 protein might remain undetected when merely relying on transcriptomic profiling tools: this is especially true for cell or tumor types with activated EGFR signaling." (PMID 23762360, 2013). "We examined tumor specimens from gefitinib- or erlotinib-treated patients with EGFR-mutant NSCLC." (PMID 23874880, 2013). "However, in P22 NBM cultures, a tumor cell population developed that showed EGFR amplification but strongly reduced EGFR expression after two months in culture." (PMID 24349039, 2013). "Cetuximab (Erbitux) is a chimeric IgG1 monoclonal antibody that competitively inhibits transforming growth factor-α (TGF-α) ligand from binding to epidermal growth factor receptor (EGFR), resulting in inhibition of tumour growth, invasion and metastasis, DNA damage repair and angiogenesis." (PMID 22745668, 2012). "Since EGFR over-expression and amplification of the EGFR locus has been linked to the presence of EGFRvIII, we used quantitative immunohistochemistry and AQUA® technology to measure EGFR expression in TMAs constructed from our patient tumor samples." (PMID 22359620, 2012). "However, there was increased expression of both HIF-2α and EGFR predominantly in the J cell-derived tumor tissue." (PMID 22768190, 2012). "Failure to downregulate EGFR signaling contributes to oncogenesis, and thus Rab7 could possess tumor suppressor activity in humans." (PMID 22558469, 2012). "Other tumor markers that play an important role in lung carcinogenesis and are implicated in the treatment response of NSCLC patients should also be evaluated, namely cyclin D1, kRAS and EGFR (epidermal growth factor receptor)." (PMID 22701665, 2012). "For instance, stabilized HIF-2α, a partner of β-catenin and often found in the hypoxic core of the tumor, upregulates the expression of epidermal growth factor receptor (EGFR) and may contribute to tumor growth." (PMID 22768190, 2012). "In a large series which identified 24 patients with B-Raf tumours having 3rd line cetuximab, 2 patients had a response but this response rate was substantially lower than patients with no mutations in the EGFR pathway (8% versus 41%)." (PMID 22991509, 2012). "Furthermore, in many tumours EGF-related growth factors are produced either by the tumour cells themselves or are available from surrounding stromal cells, leading to constitutive EGFR activation." (PMID 23202898, 2012). "Sufficient DNA was not available for additional studies for six of the tumours included in the EGFR mutation screening by direct sequencing." (PMID 22952784, 2012). "In fact, EGFR is known to regulate the production of VEGF and other proangiogenic factors, and increased VEGF expression has been associated with resistance to EGFR inhibition in a human tumor xenograft model of NSCLC." (PMID 22916093, 2012). "Thus, agents that specifically target EGFR and consequently its downstream signaling pathways are appealing candidates to enhance tumor cell killing, especially in high-expressing tumors such as SCCHN." (PMID 23150825, 2012). "This is thought to be based upon tumor dependence on the EGFR pathway." (PMID 22363766, 2012). "Therefore, 92% of ALK rearrangements in NSCLC are predicted to occur in patients whose tumours can be proven to be both EGFR and KRAS wild type." (PMID 22374459, 2012). "Targeting of the EGF receptor (EGFR) has become a standard of care in several tumor types." (PMID 23150825, 2012).
tumor (continued). "Interestingly, the clinical activity of anti-EGFR agents in patients carrying EGFR-negative tumours has already been demonstrated." (PMID 22937740, 2012). "Whilst none of the three EGFR array peptides was found among phosphosubstrates distinguishing tumor KRAS/BRAF mutation status at group level, all of the three peptides representing ERBB2 and ERBB4 were among the discriminating substrates." (PMID 23226389, 2012). "Many studies indicate that aberrant TGFα/EGFR signaling is involved in tumor progression." (PMID 22672900, 2012). "An accurate detection of EGFR microdeletions is highly recommendable, in that different deletions could have different effect on tumor development and progression or patient outcome after treatment with EGFR TKIs." (PMID 22848739, 2012). "The small numbers of B-Raf mutated patients and their poor prognosis have made it difficult to confirm the lack of responsiveness to EGFR inhibitors as robustly as has been demonstrated in the K-Ras mutated tumours." (PMID 22991509, 2012). "In more central tumour areas, the low EGFr expression may be compatible with a high level of differentiation and reduced tumour cell proliferation." (PMID 22920680, 2012). "Elevated expression of EGFR and/or its ligands is common in many types of epithelial cancer, and such change has been shown to be an important component for maintaining the proliferative capacity of the tumor cells." (PMID 23118721, 2012). "However, analysis of the subset of patients in the trial who had tissue available for testing suggests that the benefit was primarily driven by those who did have EGFR mutant tumours." (PMID 22666589, 2012). "Interestingly, SSTR expression is positively correlated with tumor size, whereas inversely correlated with EGFR expression levels and tumor differentiation." (PMID 24281555, 2012). "HGF treatment rescued EGFR inhibited tumor cells, indicating that pathways similar to those present in the NMuMG and MCF-10A mammary cells may also be used by cancer cells to sustain their growth." (PMID 23028720, 2012). "The ideal situation could be to use assay methods to allocate patients to various treatment schedules on the basis of individual measurements of tumour cell radiosensitivity (for example, due to varied expression of EGFr) or absorption of drugs." (PMID 22713695, 2012). "Of note, a similar pattern of EGF and p-EGFR expression was observed in LMS stem-like cell-based tumor xenografts, confirming that this experimental model may provide a suitable tool for preclinical testing of EGFR inhibition." (PMID 23056514, 2012). "Levels of EGFR, phosphorylated and total Akt in tumor samples were detected by western blotting." (PMID 22355336, 2012). "Thus, it appears that decreased EGFR was sufficient to reduce the size of osteolytic lesions and tumor volume within bone." (PMID 22276166, 2012). "Thus, the survival benefits seen with nimotuzumab do not appear to correlate with the inhibition of the downstream signaling molecules of EGFR and suggest alternative mechanisms of enhanced tumor cell killing." (PMID 23150825, 2012). "However, patients with tumours showing wild-type EGFR also showed benefit when they developed an erlotinib-related rash." (PMID 23078958, 2012). "Therefore, on the border of the tumour, the EGFr over-expression would be compatible with a low level of differentiation and rapid tumour growth (as from Steel’s formula)." (PMID 22920680, 2012). "The EGFR pathway is known to play important roles in cell proliferation, resistance to apoptosis, adhesion, motility, invasion and angiogenesis, all of which are characteristic features of tumor progression." (PMID 22623992, 2012). "Authors have found the co-expression of EGFR and Neu/ErbB2 was also over expressed in transitional cell cancers in ureter or renal pelvis, and that degree of expression was correlated with the histopathological grade of tumor and degree of invasion." (PMID 22754462, 2012).
tumor (continued). "Significant differences in EGFR IHC expression between a patient’s primary tumor and their metastatic tissue specimen may be another explanation." (PMID 22043994, 2012). "Inconsistent methodology and interpretation of EGFR IHC expression in tumor samples may be an explanation for this." (PMID 22043994, 2012). "Interestingly, alveolar tumors regressed after dox withdrawal, suggesting that neoplasia is dependent on active EGFR signaling, consistent with previous reports." (PMID 23285300, 2012). "Therefore, EGFR, pAKT, and hypoxia were immunohistochemically stained in tumor sections to visualize their spatial relationship and to find a possible explanation for the absence of a correlation between the in vitro and in vivo expression of pAKT." (PMID 23046567, 2012). "It has now been conclusively demonstrated that patients with activating K-Ras mutations in the tumour do not benefit from therapy with EGFR-targeted therapy." (PMID 22991509, 2012). "c-erb-B2, EGFR, mTOR, ERCC1 overexpression levels, and loss of p27 may play roles in hepatocarcinogenesis and may be significant predictors of aggressive tumor behavior." (PMID 23162604, 2012). "In particular, noninvasive targeting imaging of early EGFR responses to medical therapy could indicate effectiveness, whereas particularly when tumor volume shrinkage is often delayed response to therapy using traditional extracellular space contrast agents." (PMID 23029451, 2012). "The presence of a K-ras mutation in a tumour is now widely accepted as a negative predictive factor for response to anti-EGFR antibody treatment." (PMID 22666589, 2012). "Therefore we found that in this transgenic model, ErbB2 activation that drives tumor growth is coupled to EGFR kinase activity, which is fundamental for cell viability." (PMID 23028720, 2012). "Although a large numbers of epigenetic data have accumulated but no follow-up studies have been reported in which the promoter methylation of EGFR genes in tumour cells of primary and secondary GB were compared before and after the clinical recurrence and histological progression." (PMID 22264301, 2012). "For example, the thickness of tumor sections might affect the EGFR GCN detected, with thinner sections possibly responsible for a lower GCN cutoff value." (PMID 22897982, 2012). "EGFR overexpression was also associated with both an increased risk of local relapse and an adverse overall survival, independent of tumor stage." (PMID 22384257, 2012). "Understanding how EGFR and Src regulate αvβ5-mediated tumor cell metastasis could lead to novel therapeutic strategies to prevent the metastatic spread of human cancers." (PMID 22586492, 2012). "Thus, the phase III FLEX study involving patients with advanced NSCLC showed a strong correlation between high tumour EGFR overexpression and the efficacy of adding cetuximab to platinum based first-line chemotherapy." (PMID 23234355, 2012). "In addition to the full-length EGFR (isoform a), normal and tumor cells produce soluble EGFR isoforms (sEGFR) that lack the intracellular domain." (PMID 22623992, 2012). "Alternative activation of c-Met and IGF1R abrogate the close association of EGFR with cell survival, accompanied by tumor growth that is independent of EGFR." (PMID 22815900, 2012). "In all, 60.0% (18 out of 30) of the tumours with an increased EGFR copy number presented hemi- or homozygous deletion of PTEN (87.5% of the SDCs) in contrast to only 17.1% (27 out of 158) PTEN deletion in EGFR-negative tumours (P<0.001)." (PMID 22240798, 2012). "Epidermal growth factor receptors (EGFR) suppress the tumor suppressors miR-143 and miR-145, which coordinately control multiple targets of downstream cell-signaling pathways (i.e., K-Ras or MYC, cdk6, E2F3, and G1/S-specific cyclin-D2 or CCND2) in the AOM rodent model." (PMID 23060898, 2012). "Activation of EGFR enhances tumor growth, invasion, and spreading; it also inhibits apoptosis." (PMID 22479394, 2012).